PIK3CD-AS2 (PIK3CD antisense RNA 2)
Gene: Long non-coding RNA gene on chromosome 1 (9,672,405 to 9,687,604, reverse strand). Ensembl gene ENSG00000231789.
Diseases named in the same sentence as PIK3CD-AS2 in open-access papers:
PIK3CD-AS2 is named in the same sentence as 1 disease in open-access papers, as found by Europe PMC text mining. Sharing a sentence is not in itself a finding about the gene and the disease. The quoted sentences say what the papers report.
lung adenocarcinoma (1 paper, 2020). A carcinoma that arises from the lung and is characterized by the presence of malignant glandular epithelial cells. "We found a novel lncRNA, PIK3CD antisense RNA 2 (PIK3CD-AS2), that contributes to lung adenocarcinoma (LUAD) progression." (PMID 32165621, 2020).